TYR (tyrosinase)
Diseases named in the same sentence as TYR in open-access papers (continued):
Sharing a sentence is not in itself a finding about the gene and the disease.
melanoma (continued). "In the present study, a cohort of patients SPMs (n = 20) and MPMs (n = 19), sex-matched, was analyzed with our custom NGS panel that included 32 genes involved in melanoma susceptibility (e.g., CDKN2A, BAP1, POT1) and skin/hair pigmentation (e.g., TYR, TYRP1, OCA2)." (PMID 33748184, 2020). "In addition, BPs 7.1.1 and 7.1.2 also showed dose-dependent inhibition of tyrosinase expression levels, melanin content, and intracellular tyrosinase activity in B16F10 melanoma cells." (PMID 32759739, 2020). "Hence, doses of IPA (0.5, 1.5, and 5 nM) and IOE (3, 10, and 30 μg/mL) were incubated with B16F10 melanoma cells to determine their bioactivity in cellular tyrosinase activity and α-MSH-mediated melanogenesis." (PMID 32957728, 2020). "Immunohistochemical markers used for diagnostic purposes of melanoma, e.g., HMB45 (gp100), tyrosinase, and Melan-A, are also often expressed in OcM and, thus, not able to distinguish between the different melanoma subtypes." (PMID 32718045, 2020). "Additionally, to confirm that the anti-melanogenic effect of PH in murine melanoma cells also affects normal human melanocytes, we measured the melanin content and tyrosinase activity in human epidermal melanocytes treated with PH." (PMID 32630811, 2020). "Recently, TYR expression was found to correlate with melanocyte differentiation and thus may serve to distinguish between melanoma and benign nevi." (PMID 32429485, 2020). "Individuals with darker hair may still be heterozygous carriers of deleterious TYR and OCA2 p.V443I albinism genes that will have effects on melanogenesis in the skin and so increase the risk of these hypopigmented melanomas." (PMID 32966289, 2020). "Both melanoma cells and melanocytes require the activation of tyrosinase (TYR) to produce melanin, and α-MSH and other inducers may be used to activate TYR." (PMID 32268492, 2020). "We determined the effects of these coumaric acid- and caffeic acid-linker-peptide conjugates by measuring cell viability, α-MSH-induced melanin content, tyrosinase activity, and the expression of mRNAs related to genes that control skin melanin synthesis, in human melanoma SK-MEL-2 cells." (PMID 32625101, 2020). "Compared to α-MSH or [Nle4]-α-MSH, [Nle4-D-Phe7]-α-MSH was more resistant to enzymatic degradation by serum enzymes, and it exhibited significantly increased biological activity, as determined by activation of AC and stimulation of TYR activity in mouse melanoma cells." (PMID 32882959, 2020). "We also detected melanocyte markers such as HMB45, tyrosinase and protein S100 in melanoma." (PMID 33182777, 2020). "The few studies addressing the effect of POMs in melanoma, with most of them using B16 murine melanoma cells, reported a decrease in cell viability and antitumor activity, as well as impaired cellular tyrosinase activity and melanin formation." (PMID 32252345, 2020). "Tyrosinase is another molecule with clinical value in melanoma." (PMID 33256110, 2020). "For example, the immunogenic noncHLAIp derived from the dORF in the ABCB5 gene was moderately expressed in only 37% of the melanoma cells compared to the expression of the TYR and TYRP1 genes, both of which were highly and uniformly expressed and produced confirmed immunogenic epitopes." (PMID 32157095, 2020). "The influence of THGP treatment on the tyrosinase activity of B16 4A5 melanoma cells was examined." (PMID 31561511, 2019). "Moreover, Mc-ME showed an antimelanogenic property by inhibiting the synthesis and secretion of melanin from B16F10 melanoma cells via suppression of tyrosinase activity." (PMID 31186660, 2019). "Moreover, we further evaluate BID3 tyrosinase inhibitory activity as well as characterize its regulatory role in melanin synthesis using B16F10 melanoma cells." (PMID 31921392, 2019).
melanoma (continued). "We show that indeed, SAB298 suppressed the levels of tyrosinase in melanoma cells that express the protein (YUSIK, YUKIM and YUPEET), suggesting that downregulation of this transcription factor can contribute to SAB298 inhibition of cell proliferation in some cell lines." (PMID 31040916, 2019). "The extract inhibited the proliferation of melanoma cells through inducing cell differentiation, which is characterized by proliferation inhibition, dendrite-like outgrowth, increased melanogenesis production, and an enhanced activity of tyrosinase." (PMID 31683690, 2019). "MITF is also the main transcriptional regulator of melanoma markers Tyrosinase and Melan-A/MART1." (PMID 30674989, 2019). "In this study, we investigated whether THGP inhibits melanin synthesis via the formation of a complex with L-DOPA using mushroom tyrosinase and B16 4A5 melanoma cells." (PMID 31561511, 2019). "Interestingly, we found that the expression of melanin granules and tyrosinase activity, two indications of terminal differentiation in melanoma stem cells, were both significantly increased." (PMID 31380151, 2019). "In addition, compounds 1 and 3 exhibited dose-dependent inhibitory effects in melanin and intracellular tyrosinase levels in α-melanocyte-stimulating hormone (α-MSH)-induced B16F10 melanoma cells." (PMID 31108882, 2019). "Furthermore, TMBC significantly reduced the melanin content and cellular tyrosinase activity in B16 melanoma cells, although it increased mRNA levels of cellular tyrosinase." (PMID 30791521, 2019). "Gnetol inhibited melanin production in murine B16 melanoma cells via inhibition of tyrosinase." (PMID 29522491, 2018). "It is unclear whether other common variants that have been associated with melanoma, particularly other pigmentation genes, such as SLC45A2, TYR or TYRP-1, may also exhibit a similar modifying effect CDKN2A penetrance similar to MC1R." (PMID 29774366, 2018). "The level of tyrosinase protein in the melanoma cells was measured by Western blot analysis." (PMID 30115883, 2018). "Furthermore, our USC-CM treatments are expected to inhibit the synthesis of melanin and the activity of tyrosinase in melanoma B16 cells as AD-MSC-CM do." (PMID 30417126, 2018). "Indeed, the levels of melanin and tyrosinase are being considered as indicators of differentiated melanoma cells." (PMID 30115883, 2018). "The EA antiproliferative potential against melanoma was also tested as polyphenolic whisky constituent: EA, gallic acid and lyoniresinol were the predominant whisky polyphenols and all of them significantly inhibited melanogenesis and tyrosinase activity in B16 murine melanoma cells." (PMID 30441769, 2018). "The expression of tyrosinase protein was enhanced to about 2-fold in GF-1, 4, and 9 treated cells, demonstrating that the melanogenesis promotion was partly mediated by increased tyrosinase in melanoma cells." (PMID 30115883, 2018). "To clarify whether PTFFE affects melanogenesis via inhibition of tyrosinase activity, we examined the intracellular tyrosinase activity in PTFFE-treated B16F10 melanoma cells." (PMID 30249988, 2018). "Administration of DCs electroporated with TriMix mRNA and a melanoma antigen (gp100, tyrosinase, MAGE-A3 or MAGE-C2 fused to DC.LAMP) demonstrated durable clinical benefit in clinical trials involving patients with advanced melanoma when combined with the CTLA-4 inhibitor ipilimumab." (PMID 30349530, 2018). "However, 5-HT dose dependently inhibits melanin production and tyrosinase activity in human SK-MEL-188 melanoma cells." (PMID 29922226, 2018). "They found that the expression of constitutively active BRAFV600E under the control of the tyrosinase (TYR)-promoter, which occurs specifically in melanocytes, led to melanoma formation only in conjunction with the deletion of the inhibitor of PI3K-activation, PTEN (Phosphatase and Tensin Homolog)." (PMID 30053879, 2018).
melanoma (continued). "In melanoma, the differentiation status of cells could be monitored by melanogenesis, which resulted in the conversion of l-tyrosine to l-dopa by tyrosinase." (PMID 30115883, 2018). "SECM was proposed for precisely mapping the TyR distribution in melanoma tissues." (PMID 30096895, 2018). "Therefore, MITF or its target genes (e.g., tyrosinase) is clinically and cosmetically important for the treatment of melanoma and melanin-related skin diseases." (PMID 30249988, 2018). "Since we also detected MITF and its target gene tyrosinase (TYR) to be regulated upon modification of canonical Wnt signaling in SKMEL28 melanoma cells it could be that MITF is at least partially involved in the pro-migratory effects in vitro and in vivo." (PMID 29454361, 2018). "Indeed, tyrosinase activity of B16 murine melanoma cells exposed to EA, recovered in a dose-dependent manner when copper ions were added to the medium." (PMID 30441769, 2018). "In addition, the induction of MITF and Tyrosinase expression paralleled by miR-221&222 down-modulation, showed the influence of OA also on melanoma differentiation." (PMID 29484133, 2018). "Indeed, soon after, clinical trials in human advanced melanoma patients started as well, exploiting the same strategy of xenogeneic DNA vaccination against the tyrosinase antigen." (PMID 29534457, 2018). "Additionally, lucidone exhibits anti-COX-2 and anti-tyrosinase activities in macrophages and melanoma cells, respectively." (PMID 29338543, 2018). "Here the 17-AAG dependent, tyrosinase-independent induction of melanin formation in human SK-Mel-30 melanoma cells implicates DCT and TYRP1 in facultative melanization, showing that these accessory melanogenic enzymes can modulate pigmentation without changes in tyrosinase." (PMID 29481571, 2018). "They used the ethyl acetate extract obtained from the leaves of C. azarolus and a flavonoid component of the extract named vitexin-2′′-O-rhamnoside, and demonstrated that both compounds have the ability to reduce the melanin content by inhibiting the TYR activity of mouse melanoma cell lines." (PMID 29632489, 2018). "After treatment with PN3 at concentrations of 25, 50, and 100 μg/mL, TYR expression in B16 melanoma cells was significantly reduced by 46.64%, 57.25%, and 78.85%, respectively, in a dose-dependent manner, and the expression levels of TRP-1 were decreased by 56.90%, 59.35%, and 86.99%, respectively." (PMID 29385729, 2018). "Many remissions were observed in patients with melanoma after they had receivedDC-based vaccines loaded with a mixture of mRNAs encoding TAAs MAGE-A1,-A3,-C2,tyrosinase, MelanA/MART-1 and gp100 fused with HLA II-targeting sequences, incombination with IFN-α-2b injections." (PMID 29104773, 2017). "The role of carbohydrates in melanogenesis has been highlighted by studies investigating glycosylation and glycosyltransferase in the pigmentation phenotype of melanomas, and on the sugar residues for catalytic activity of tyrosinase, a key enzyme involved in melanin synthesis." (PMID 29045474, 2017). "The investigation demonstrated that MNZQ can inhibit cell proliferation of melanoma without inhibiting tyrosinase activity and play a key role in causing autophagy in B16 cells." (PMID 29197358, 2017). "In contrast, tyrosinase expression and surface metastases were significantly (p < 0.01 and 0.001, respectively) reduced in CXCR3-deficient mice, demonstrating that host cell expression of CXCR3 impacts melanoma engraftment or maintenance in the lungs." (PMID 28358049, 2017). "The cell line exhibits well known melanoma markers such as Melan-A, S-100, Tyrosinase, and HMB-45." (PMID 28522871, 2017). "To examine whether Gomisin N inhibits tyrosinase activity in vitro, we used mushroom tyrosinase and B16 melanoma cell lysates." (PMID 28241436, 2017).
melanoma (continued). "Cellular tyrosinase assay showed that PR-NLCs could significantly inhibit tyrosinase activity in melanoma cells, suggesting that NLCs can be used as a biocompatible nanocarrier for the effective delivery of skin whitening agents." (PMID 28846658, 2017). "CGA is likely a substrate of melanin, but its metabolic products may suppress melanogenesis in B16 melanoma cells by inhibiting tyrosinase activity." (PMID 28777326, 2017). "A cellular uptake study and tyrosinase inhibition assay on B16F10 cells indicated that NLCs could efficiently deliver PR into melanoma cells." (PMID 28846658, 2017). "However, the cellular tyrosinase activity in B16 melanoma cell lysates was significantly downregulated by Gomisin N both with and without α-MSH treatment." (PMID 28241436, 2017). "Fucoxantin was reported to suppress TYR activity and melanogenesis in B16 murine melanoma cells." (PMID 28946635, 2017). "Therefore, we assessed tyrosinase expression in lungs 24 h post-injection as a quantitative measure of melanoma engraftment." (PMID 28358049, 2017). "However, when treated to B16 melanoma cells, Gomisin N resulted in a decrease in tyrosinase activity of the cell lysate in a dose-dependent manner." (PMID 28241436, 2017). "Other serum biomarkers for melanoma include tyrosinase, osteopontin, IL-8 etc." (PMID 28567163, 2017). "It was speculated that CGA has two side-roles in melanogenesis of B16 melanoma cells as it exhibited different effects on melanogenesis and tyrosinase as the incubation time was extended." (PMID 28777326, 2017). "However, recently the use of nanoparticles (NP) containing mRNA encoding the melanoma antigens, NY-ESO-1, tyrosinase, MAGE-A3, and a novel CTA TPTE (a transmembrane phosphatase), has shown early clinical promise in a pilot study of three patients." (PMID 29276510, 2017). "To determine whether the thiopurine-drugs inhibit mammalian tyrosinase, we performed an enzymatic assay with melanoma B16F10 cell lysates." (PMID 29283382, 2017). "Therefore, we evaluated the expression of the Cre recombinase gene under the control of the melanocyte-specific tyrosinase (Tyr) promoter to allow the specific induction of melanomas." (PMID 27999416, 2016). "Tyrosinase, the rate-limiting enzyme controlling the synthesis of melanin pigment, has been validated as one of the key immunohistochemical markers for amelanotic melanomas." (PMID 27166257, 2016). "Furthermore, six SNPs in TYR, SILV/CDK2, GPR143, and F2RL1 showed strong differences in melanoma risk by sex (P < 0.01)." (PMID 26998216, 2016). "In melanoma, the effect of quercetin can be amplified due to tyrosinase activity." (PMID 27843913, 2016). "By exploiting the characteristics of quercetin and the expression of tyrosinase, therapies could be developed that specifically target melanoma and preserve or protect normal tissue." (PMID 27843913, 2016). "In general, quercetin could be used to exploit tyrosinase activity to prevent, and/or treat, melanoma with minimal additional side effects." (PMID 27843913, 2016). "CGA is a likely substrate of melanin, but the metabolic product of CGA may suppress melanogenesis in B16 melanoma cells by inhibiting tyrosinase activity." (PMID 26901191, 2016). "In the melanoma model, expression of BrafV600E from an LSL-BrafV600E allele is driven in melanocytes by a tamoxifen-activated version of Cre recombinase under the control of the melanocyte-specific tyrosinase promoter (Tyr-CreERT2)." (PMID 26765561, 2016). "Moreover, alternol increases the expression levels of tyrosinase, the tyrosinase-related proteins 1 and 2 to induce mouse melanoma B16F0 cell differentiation and inhibit cell proliferation, characterized by the enhanced melanin content and tyrosinase activity." (PMID 27796318, 2016).
melanoma (continued). "We used B16F10 melanoma cells as a model system to investigate the effects of LASAP-C on anti-melanogenesis and evaluated the underlying molecular mechanisms such as the effect on the expression of tyrosinase, tyrosinase-related protein (TRP)-1, and TRP-2." (PMID 27424198, 2016). "Stage III and IV melanoma patients were vaccinated via intranodal injection (12 patients) or combined intradermal/intravenous injection (16 patients) with VAC-DC loaded with keyhole limpet hemocyanin (KLH) and mRNA encoding tumor antigens gp100 and tyrosinase." (PMID 26861670, 2016). "Overall quercetin could be used to exploit tyrosinase activity to prevent, and/or treat, melanoma with minimal additional side effects." (PMID 27843913, 2016). "Importantly, Stat3 activity increased melanoma invasiveness and is required for active melanogenesis by regulating tyrosinase gene expression and enzyme activity." (PMID 26830149, 2016). "By focusing on these areas, quercetin could be used to exploit tyrosinase activity, as well as prevent, and/or treat, melanoma with minimal additional side effects." (PMID 27843913, 2016). "Xenogenic DNA vaccination against the melanoma differentiation antigens glycoprotein (gp) 100 and tyrosinase (tyr) have been shown to overcome auto-tolerance and to elicit an immune response in mice, dogs, and humans and a clinical antitumoral effect in mice and dogs." (PMID 25967290, 2015). "Interestingly, cells incubated with hUCB-MSC-CM more efficiently suppressed the α-MSH-induced pigmentation than that of arbiun, a strong tyrosinase inhibitor in melanocytes and melanoma cells." (PMID 26024475, 2015). "Thus, in the present study, we provide evidence that Hex, Chlo, EA and MeOH extracts exposure effectively stimulate tyrosinase activity and melanogenesis in B16-F10 melanoma cells in a concentration dependent manner." (PMID 26329604, 2015). "In addition, the inhibitory effect of leaf extracts on tyrosinase activity and melanin production was examined in murine melanoma B16F10 cells." (PMID 26500815, 2015). "There are no reports about the immunogenicity of human gp100 (hgp100) to horses, and clinical study results on the anti-melanoma effect of DNA-encoded xenogenic tyrosinase and gp100 in grey horses have not been published to date." (PMID 25967290, 2015). "In addition, the underlying mechanisms of the effects of PCP on melanin synthesis were explored in B16F10 melanoma cells by determining free radical scavenging capacity, tyrosinase activity, and melanin content." (PMID 26473849, 2015). "Tyrosinase and gp100 were found to be (over-)expressed in equine melanoma lesions." (PMID 25967290, 2015). "TNF-α was reported to inhibit the expression of tyrosinase in B16 melanoma cells." (PMID 25853464, 2015). "In melanoma, RT-qPCR is one of the most widely used methods for the indirect detection of CTCs, demonstrating high sensitivity through the detection of marker RNA expression such as tyrosinase mRNA coding for a melanocyte-specific enzyme." (PMID 26779490, 2015). "In murine melanoma B16-F10 cells, we demonstrated that it suppressed melanin production, reduced the protein expression of melanosome maturation related proteins, and inhibited tyrosinase activity." (PMID 26343635, 2015). "Tyrosine and l-DOPA are also bioregulatory agents acting not only as inducers and positive regulators of melanogenesis, but also as regulators of other cellular functions, so low concentrations of CGA can enhance melanogenesis and tyrosinase activity of B16 murine melanoma cells." (PMID 25157464, 2014). "This changed when several groups characterized immunogenic melanoma-associated MHC class II epitopes of the tumor antigens gp100 and tyrosinase leading to a comparative study of melanoma patients treated with moDCs pulsed with both MHC class I and class II epitopes or MHC class I epitopes alone." (PMID 24782868, 2014).